PRR30 (proline rich 30)
Synonyms: C2orf53; MGC44505
Tractability: No criterion of Open Targets' tractability assessment is met for any kind of drug.
Gene: Protein-coding gene on chromosome 2 (27,136,848 to 27,139,410, reverse strand). Ensembl gene ENSG00000186143.
Gene Ontology:
Molecular function: protein binding
Genetic constraint (gnomAD): Loss-of-function variants: 1 observed, 1.2 expected, observed/expected ratio (o/e) 0.84, 90% interval 0.24 to 1.87. That is too few expected variants to judge how well the gene tolerates losing a copy. Missense variants: 546 observed, 547.58 expected, observed/expected ratio (o/e) 1, 90% interval 0.93 to 1.07. Synonymous variants: 229 observed, 233.43 expected, observed/expected ratio (o/e) 0.98, 90% interval 0.88 to 1.1.
Homologues: Orthologues: macaque PRR30 (93% identical), rat Prr30 (56% identical), mouse Prr30 (53% identical).